CRYBB2 (crystallin beta B2)
Description:
Crystallins are the dominant structural components of the vertebrate eye lens.
Synonyms: CRYB2; CRYB2A; CCA2; CTRCT3; D22S665
Tractability: No criterion of Open Targets' tractability assessment is met for any kind of drug.
Target class: Structural protein
Gene: Protein-coding gene on chromosome 22 (25,212,564 to 25,231,870, forward strand). Ensembl gene ENSG00000244752.
Subcellular location (Human Protein Atlas): Nucleoplasm
Gene Ontology:
Molecular function: identical protein binding; protein binding; structural constituent of eye lens; structural molecule activity
Biological process: lens development in camera-type eye; visual perception; camera-type eye development
Genetic constraint (gnomAD): Loss-of-function variants: 11 observed, 23.8 expected, observed/expected ratio (o/e) 0.46, 90% interval 0.29 to 0.76. The upper end of that interval is the gene's LOEUF score, 0.76, which puts it in group 3 of 6, group 1 being the genes least tolerant of losing a copy. Missense variants: 173 observed, 248.14 expected, observed/expected ratio (o/e) 0.7, 90% interval 0.62 to 0.79. Synonymous variants: 84 observed, 91.96 expected, observed/expected ratio (o/e) 0.91, 90% interval 0.76 to 1.1.
Homologues: Orthologues: macaque CRYBB2 (99% identical), dog CRYBB2 (99% identical), guinea pig CRYBB2 (99% identical), pig CRYBB2 (98% identical), mouse Crybb2 (97% identical), rat Crybb2 (97% identical), rabbit CRYBB2 (93% identical), tropical clawed frog crybb2 (83% identical), zebrafish crybb2 (75% identical), chimpanzee CRYBB2 (50% identical). Paralogues in human: CRYBB3 (53% identical), CRYBB1 (51% identical), CRYBA1 (41% identical), CRYBA4 (38% identical), CRYBG1 (37% identical), CRYBA2 (36% identical), CRYBG2 (30% identical), CRYGS (29% identical), CRYBG3 (28% identical), CRYGA (28% identical), CRYGC (28% identical), CRYGD (28% identical), and 2 more.
Diseases named in the same sentence as CRYBB2 in open-access papers:
CRYBB2 is named in the same sentence as 36 diseases in open-access papers, as found by Europe PMC text mining. Sharing a sentence is not in itself a finding about the gene and the disease. The quoted sentences say what the papers report.
cataract (20 papers, 2008 to 2023). Partial or complete opacity of the crystalline lens of one or both eyes that decreases visual acuity and eventually results in blindness. "For example, cataracts (where recorded) varied between and within the four families with CRYBB2 mutations, including anterior/posterior subcapsular and blue dot, dense central, sutural/blue dot and blue dot (only) cataract types." (PMID 33494148, 2021). "Despite the association of numerous mutations with cataracts, missense mutations in crystallin genes, particularly CRYAA and CRYBB2, are considered the primary cause of autosomal dominant cataracts." (PMID 29259299, 2017). "Mutations in the CRYBB2/Crybb2 gene lead to cataracts, which are characterized by the loss of lens transparency." (PMID 24096375, 2013). "In the mouse, three mutant alleles of Crybb2 cause progressive cataracts which all affect exon 6 and therefore the fourth Greek key motif." (PMID 22312185, 2012). "Over half of these strains carry mutations in six crystallin genes (Cryaa, Cryba1, Crybb2, Crygc, Crygd, and Crygs) that are syntenic with human counterparts linked with cataract, thereby providing relevant mouse models for human cataract." (PMID 21042563, 2010). "Previous studies found homozygous changes in CRYBB2 that were associated with severe microphthalmia and cataract and found an interaction of CRYBB2–CRYBA4 monomers." (PMID 20577656, 2010). "So far, there have been eight reports in the literature of CRYBB2 gene mutations causing congenital cataracts." (PMID 18449377, 2008). "These cataract phenotypes were previously reported to be associated with the CRYBB2 gene, representing that the same gene mutation may cause different cataracts." (PMID 37680813, 2023). "Among the upregulated Mendelian cataract disease-associated genes were several crystallins (CRYAB and CRYBB2) and mitochondrial encoded genes (MT-ATP6, MT-ND1, and MT-CO2)." (PMID 35348588, 2022). "There is also a need to explore animal models to elucidate the underlying molecular mechanism by which CRYBB2 and CRYGD variants contribute to cataracts." (PMID 34840822, 2021). "We identified three mutations being most likely causative for congenital or childhood cataracts in these families from India – one affects the GJA3 gene encoding connexin 46, the other two affect CRYBB2 encoding β-crystallin." (PMID 21031021, 2010). "Meanwhile, the Crybb2 knockout mice could develop cataracts 6–8 weeks after birth and cataract severity increased with age." (PMID 28025620, 2016). "As much as 70% of autosomal dominant cataract may be accounted for by missense coding mutations in the genes for crystallins, particularly CRYAA, CRYBB2, and CRYGD, and connexins (GJA3, GJA8)." (PMID 21042563, 2010).
breast carcinoma (9 papers, 2009 to 2023). "High expression of CRYBB2/CRYBB2P1 is associated with higher breast cancer-related mortality in African-American women, likely in relation to enhanced tumor cell proliferation." (PMID 34118792, 2021). "Of note, CRYBB2 is DE by RRE in diseased and normal tissue and is associated with poor prognosis in breast cancer." (PMID 36127808, 2023). "CRYBB2 associated with the WNT pathway was overexpressed in Black patients and other studies in colon and breast cancer have shown promising results for targeting of the WNT pathway with small molecules, peptides and blocking antibodies." (PMID 28029648, 2017). "Similar to the breast cancer findings mentioned in the previous section, a 2008 study comparing gene expression profiles of prostate tumors from African American and Caucasian men pointed out a two-gene signature comprising CRYBB2 and PSPHL that accurately differentiated between these two groups." (PMID 34118792, 2021). "Interestingly, a more recent study provided additional evidence that upregulation of the pseudogene CRYBB2P1, and not CRYBB2, is associated with race and poor outcome in breast cancer and possibly other tumors." (PMID 34118792, 2021). "Of note, this finding was consistent with a previous study that combined CRYBB2 and PSPHL expression data to reliable distinguish African American from Caucasian breast cancer samples." (PMID 34118792, 2021). "At gene level, AA women with breast cancer showed higher expression of several key cell cycle regulating genes, including CCNE2, CCNB1, CCNA1, CDKN2A and other tumor related genes CRYBB2, TMPO, AMFR, PSPHL, which directly impact the development and aggressiveness of tumors." (PMID 32824813, 2020).
prostate carcinoma (8 papers, 2009 to 2025). A carcinoma that arises from epithelial cells of the prostate gland. "In turn, a case-control association study reported that a genetic variant in the CRYBB2 gene (rs9608380) is associated with the risk of prostate cancer in African Americans." (PMID 34118792, 2021). "CRYBB2 in germline analyses is associated with prostate cancer in Black men." (PMID 36127808, 2023). "Expression of CRYBB2 was also increased in a study comparing AA and CA colorectal cancer and in another study comparing AA and CA prostate cancer." (PMID 24324792, 2013). "Similarly, compared to Caucasians, upregulation of CRYBB2 is observed also in African-American patients with colorectal cancer, prostate cancer, renal cell carcinoma, and glioblastoma." (PMID 34118792, 2021). "We previously had demonstrated that PSPHL and CRYBB2 could be used as a two gene classifier to differentiate between African-American and European-American prostate cancer patients." (PMID 19225562, 2009). "Previous investigations identified a two-gene tumor signature (CRYBB2 and PSPHL) that accurately differentiated between African-American and European-American prostate cancer patients." (PMID 22276153, 2012). "One hundred sixty-one genes were differentially expressed in the stage II comparison (134 increased and 27 decreased) including crystallin, beta B2 (CRYBB2; 2.00 log2 fold-change; P = 3.27E-10) which was differentially expressed in AA breast, colorectal, and prostate cancers." (PMID 24324792, 2013). "Expression was higher in AA men and along with CRYBB2 was an accurate two gene classifier for AA status in prostate cancer tissue but not corresponding normals." (PMID 22783543, 2012).
congenital cataracts (6 papers, 2008 to 2023). "This is the sixth reported case of a C.C475T mutation causing congenital cataracts, providing further evidence that CRYBB2 is a pathogenic gene for congenital cataracts and that this site is a hot spot for CRYBB2 mutation." (PMID 18449377, 2008). "Previous CRYBB2 gene mutations associated with congenital cataracts." (PMID 21245961, 2011). "The CRYBB2 gene’s function in congenital cataracts may be better understood as a result of the finding of a mutation in the gene." (PMID 37680813, 2023). "A subset of the 7-days radiation only DEG (Cryaa, Cryba1, Cryba2, Cryba4, Crybb1, Crybb2, Crybb3, Crygs, Bsfp1) were enriched in nuclear and congenital cataracts, however, these genes were not dysregulated at 1 month or 4 months." (PMID 36207342, 2022).
autosomal dominant congenital cataract (4 papers, 2009 to 2023). "This study aimed to investigate the novel silent mutation in CRYBB2 of exon six in the Pakistani families of Autosomal Dominant Congenital Cataracts (ADCC)." (PMID 37680813, 2023). "This study identified a missense mutation in CRYBB2 in a family of Basotho with autosomal dominant congenital cataract (ADCC)." (PMID 19649175, 2009).
schizophrenia (4 papers, 2019 to 2022). A major psychotic disorder characterized by abnormalities in the perception or expression of reality. "In addition, we found hypo-methylation and downregulation of two crystalline genes, CRYBB1 and CRYBB2, which were previously found to be associated with schizophrenia and autism-like behavior." (PMID 36012404, 2022). "Here, in addition to a genetic association study in schizophrenia patients and healthy controls, we report converging evidence that polymorphisms in the CRYBB2 gene and its flanking regions are linked to altered CRYBB2 mRNA expression, antisaccade task performance, and working memory performance." (PMID 32317624, 2020). "To verify the results found in mice, we genotyped 27 single nucleotide polymorphisms (SNPs) within the CRYBB2 gene and its flanking regions and investigated different schizophrenia typical endophenotypes in a sample of 510 schizophrenia patients and 1322 healthy controls." (PMID 32317624, 2020). "Notably, a meta-analysis of gene expression in the human cortex illustrated that the CRYBB2 gene shows the most significant association with five psychiatric disorders, namely attention-deficit hyperactivity disorder, autism, major depressive disorder, bipolar disorder, and schizophrenia." (PMID 34118792, 2021). "Based on these findings, CRYBB2 appears to be an interesting candidate gene for schizophrenia, a complex and multifactorial psychiatric disease in which genetic factors play a major role." (PMID 32317624, 2020). "Mutations in the mouse Crybb2 gene give rise to alterations in prepulse inhibition (PPI; an operational measurement of sensorimotor gating) and reduce hippocampal size, i.e., features typical of patients with schizophrenia." (PMID 34118792, 2021). "Crybb2 is also expressed in the brain, and in homozygous Crybb2 mutants, parvalbumin-positive interneurons as well as dendrites and dendritic branches in the hippocampus are decreased, and eventually changes in schizophrenia-related endophenotypes have been observed." (PMID 30919050, 2019).
breast tumors (3 papers, 2009 to 2023). "In accordance with the prostate study, the two gene signature consisting of probesets for PSPHL (205048_s_at) and CRYBB2 (206777_s_at) was identified as the top-ranked predictor that can distinguish between the breast tumor epithelia from African-Americans and European-Americans." (PMID 19225562, 2009). "Both CRYBB2 and its pseudogene CRYBB2P1 are expressed in higher amounts in AA vs. EA breast tumors." (PMID 34071280, 2021).
colorectal cancer (3 papers, 2013 to 2021). A primary or metastatic malignant neoplasm that affects the colon or rectum. "Another report, dating back to 2012, described significant upregulation of CRYBB2 in colorectal cancer samples from African-American patients compared to European Americans." (PMID 34118792, 2021).
diabetes (3 papers, 2011 to 2018). "Crystallin isoforms Cryaa (α-crystallin A), Crybb2 (β-crystallin B2), Cryab (α-crystallin B) and Cryba3 (β-crystallin A3) were confirmed to be induced after 3 months of diabetes." (PMID 21249158, 2011).
glaucoma (3 papers, 2020 to 2023). Increased pressure in the eyeball due to obstruction of the outflow of aqueous humor. "Among those, six genes (Lyz2, Apoe, Crybb2, Pvalb, Cryab, Mmp3) were found to be associated with glaucoma when compared with the reference glaucoma genes." (PMID 37377596, 2023). "Mutants in CRYBB2 were also associated with anterior segment dysplasia, including microcornea and glaucoma." (PMID 34722561, 2021). "Perhaps the most compelling evidence of the significance of CRYBB2 for retina neuroprotection has been that its intravitreal injection at the time of IOP elevation improves retinal ganglion cell survival in a rat model of glaucoma combined with mass spectrometry-based proteomics experiments." (PMID 32012756, 2020).
microphthalmia (3 papers, 2010 to 2025). Congenital or developmental anomaly in which the eyeballs are abnormally small. "Here, we report a patient suffering from microphthalmia, microcornea, CC (OMIM 601547), and BVMD caused by novel heterozygous variants in BEST1 and CRYBB2 (OMIM 123620)." (PMID 37076855, 2023). "Previous studies have reported that some variants in crystallin genes (e.g., CRYBB1, CRYBB2, CRYAA, and CRYGC) could lead to a combined occurrence of CC and other ocular abnormalities, such as microcornea, microphthalmia, coloboma, and glaucoma." (PMID 37076855, 2023).
nuclear cataract (3 papers, 2011 to 2023). A cataract (disease) that involves the lens nucleus. "Notably, the mutation of CRYBB2 may cause congenital nuclear cataracts in humans." (PMID 34946810, 2021).
ocular hypertension (2 papers, 2011 to 2024). Abnormally high intraocular pressure. "Previous studies have reported upregulation of CRYBB2 expression in various ocular pathologies, including age-related macular degeneration, glaucomatous neuropathy, cauterization-induced ocular hypertension in rats, and ocular hypertension in rats." (PMID 39318470, 2024).
albinism (1 paper, 2020). A congenital disorder characterized by partial or complete absence of melanin pigment in the eyes, hair, or skin. "The genes identified for MAC were KMT2D, MAB2IL2, ALDH1A3; ASDA were KERA, PAX6, MYOC, TGFBI, and SLC4A11; congenital cataract were CRYBB2, EPHA2, HSF4 and BCOR; infantile nystagmus were CACNA1A and FRMD7; and albinism were OCA2, GPR143, HPS6 and SLC38A8." (PMID 32830442, 2020).
Coats disease (1 paper, 2016). Coats disease (CD) is an idiopathic disorder characterized by retinal telangiectasia with deposition of intraretinal or subretinal exudates, potentially leading to retinal detachment and unilateral blindness. "Of the identified DCPs, several crystalline-related proteins, including CRYBB1, CRYBB2, CRYGS and CRYGD, were down-regulated in the AH from patients with Coats' disease." (PMID 27416065, 2016).
glioma (1 paper, 2024). A benign or malignant brain and spinal cord tumor that arises from glial cells (astrocytes, oligodendrocytes, ependymal cells). "However, a recent analysis identified CRYBB2 as one of 13 genes significantly associated with increased survival in African American glioma patients compared to Caucasian American glioma patients." (PMID 39318470, 2024).
kidney cancer (1 paper, 2024). Primary or metastatic malignant neoplasm involving the kidney. "Results for CRYBB2P1 were at first sight compatible with (loss-of-) imprinting in kidney cancer, yet we deem this result to be more likely to be caused by a cis-eQTL effect, possibly compounded by mismapping of reads between the CRYBB2P1 pseudogene and its CRYBB2 ancestral gene (see Section 4)." (PMID 39199324, 2024).
renal cell carcinoma (1 paper, 2021). "Moreover, a study analyzing the significant disparities in survival between black and white patients with renal cell carcinoma showed that CRYBB2 was overexpressed in black patients associated in association with the WNT signaling pathway." (PMID 34118792, 2021).
retinal ischemia (1 paper, 2007). A ischemic disease that involves the retina. "A microarray study on retinal ischemia reported an upregulation of Cryaa, Cryab, Cryba1/3, Crybb2, Crygc, and Grifin transcript levels after 12 h of reperfusion, but no qPCR validation was presented." (PMID 17327827, 2007).
uveitis (1 paper, 2012). An inflammatory process affecting a part of or the entire uvea. "Crystallins that belong to the small heat shock protein family have a non-structural role, and retina-specific elevated levels of Cryaa, Cryba1, Crygs, Crybb2, Crygb, and Crygc have been reported in experimental uveitis." (PMID 22605924, 2012).